RN7SL68P (RNA, 7SL, cytoplasmic 68, pseudogene)
Gene: Miscellaneous RNA gene on chromosome 5 (141,479,316 to 141,479,625, forward strand). Ensembl gene ENSG00000242020.
Homologues: Orthologues: chimpanzee Metazoa_SRP (97% identical), macaque Metazoa_SRP (92% identical). Paralogues in human: RN7SL2 (78% identical), RN7SL1 (77% identical), RN7SL300P (77% identical), RN7SL709P (77% identical), RN7SL3 (76% identical), RN7SL127P (75% identical), RN7SL658P (75% identical), RN7SL769P (75% identical), RN7SL304P (75% identical), RN7SL444P (75% identical), RN7SL118P (75% identical), RN7SL607P (75% identical), and 699 more.